HSPE1 (heat shock protein family E (Hsp10) member 1)
Description:
Co-chaperonin implicated in mitochondrial protein import and macromolecular assembly. Together with Hsp60, facilitates the correct folding of imported proteins. May also prevent misfolding and promote the refolding and proper assembly of unfolded polypeptides generated under stress conditions in the mitochondrial matrix. The functional units of these chaperonins consist of heptameric rings of the large subunit Hsp60, which function as a back-to-back double ring. In a cyclic reaction, Hsp60 ring complexes bind one unfolded substrate protein per ring, followed by the binding of ATP and association with 2 heptameric rings of the co-chaperonin Hsp10. This leads to sequestration of the substrate protein in the inner cavity of Hsp60 where, for a certain period of time, it can fold undisturbed by other cell components. Synchronous hydrolysis of ATP in all Hsp60 subunits results in the dissociation of the chaperonin rings and the release of ADP and the folded substrate protein (Probable).
Synonyms: Hsp10; CPN10; EPF; GroES
Tractability: Small molecule: a structure with a bound ligand is known; a high-quality ligand is known. PROTAC: ubiquitination databases record sites on it; its protein half-life has been measured; a small molecule that binds it is known.
Gene: Protein-coding gene on chromosome 2 (197,500,140 to 197,503,461, forward strand). Ensembl gene ENSG00000115541.
Subcellular location: Mitochondrion matrix
Pathways (Reactome):
Cellular responses to stimuli: Mitochondrial unfolded protein response (UPRmt)
Signal Transduction: RHOG GTPase cycle
Gene Ontology:
Molecular function: protein binding; protein-folding chaperone binding; RNA binding; metal ion binding; ATP binding; protein folding chaperone
Biological process: osteoblast differentiation; intrinsic apoptotic signaling pathway; protein folding; response to unfolded protein
Cellular component: extracellular exosome; membrane; mitochondrion; mitochondrial matrix
Genetic constraint (gnomAD): Loss-of-function variants: 1 observed, 7.5 expected, observed/expected ratio (o/e) 0.13, 90% interval 0.046 to 0.63. That is too few expected variants to judge how well the gene tolerates losing a copy. Missense variants: 42 observed, 66.9 expected, observed/expected ratio (o/e) 0.63, 90% interval 0.49 to 0.81. Synonymous variants: 24 observed, 23.73 expected, observed/expected ratio (o/e) 1.01, 90% interval 0.73 to 1.42.
Homologues: Orthologues: chimpanzee HSPE1 (100% identical), rabbit HSPE1 (100% identical), mouse Hspe1 (96% identical), mouse Hspe1-rs1 (94% identical), tropical clawed frog hspe1 (86% identical), zebrafish hspe1 (80% identical), rat Hspd1l2 (78% identical), Caenorhabditis elegans Y22D7AL.10 (62% identical), Drosophila melanogaster CG11267 (54% identical), Drosophila melanogaster CG9920 (50% identical).
Diseases named in the same sentence as HSPE1 in open-access papers:
HSPE1 is named in the same sentence as 99 diseases in open-access papers, as found by Europe PMC text mining. Sharing a sentence is not in itself a finding about the gene and the disease. The quoted sentences say what the papers report.
prostate carcinoma (6 papers, 2015 to 2026). A carcinoma that arises from epithelial cells of the prostate gland. "Our investigation yielded novel findings, as we observed that the depletion of HSF1 in prostate cancer cell lines resulted in a decrease in HSPE1 expression and heightened susceptibility to ferroptosis triggered by the RSL3." (PMID 37351671, 2023). "In addition, HSF1 alleviates ROS and MDA levels to enhance the resistance of prostate cancer cells to ferroptosis by regulating HSPE1 in vitro, and HSF1 knockout promotes the susceptibility of PC to RSL3 treatment by increasing ferroptosis in vivo." (PMID 37351671, 2023). "After screening the downstream proteins of HSF1, we found that HSPE1 exhibited the strongest correlation with HSF1 in prostate cancer, and HSPE1 mainly functions in maintaining the mitochondrial ETC." (PMID 37351671, 2023). "A recent study discovered that HSF1 enhances prostate cancer cell resistance to ferroptosis by modulating HSPE1, and that HSF1 knockdown can promote prostate cancer cell sensitivity to RSL3 therapy." (PMID 37868994, 2023). "In summary, the upregulation of HSF1 and HSPE1 may have significant implications in the development of prostate cancer, particularly in relation to cellular proliferation and defense against oxidative stress." (PMID 37351671, 2023). "In conclusion, HSF1 may alleviate ROS and MDA levels to enhance the resistance of prostate cancer cells to ferroptosis by regulating HSPE1." (PMID 37351671, 2023). "Studies have confirmed that HSPE1 is highly expressed in the leukemia stem cells of childhood AML, and other research indicated that upregulation of HSPE1 promoted prostate cancer progression." (PMID 38919521, 2024). "Given that bioinformatics analysis has shown that HSPE1 is mainly involved in the function of the ETC in mitochondria, HSF1/HSPE1 potentially represent crucial molecules affecting ROS levels in prostate cancer." (PMID 37351671, 2023).
breast carcinoma (5 papers, 2018 to 2021). "All this data together suggest that not only the TRiC complex has a protagonist role in cancer behaviour but also that the HSPD1/HSPE1 complex is involved tightly with TRiC in proteostasis regulation, an association that is poorly understood in breast cancer and should be further studied." (PMID 29954368, 2018). "Hsp90AA1, Hsp90AB1, TRAP1, HspA5, HspB1, HspE1, HspD1, HspA1B, HspA8, HspA9, and HspA4 were validated as potential biomarkers for breast cancer tissue." (PMID 31921692, 2019). "Multiple heat shock proteins, including Hsp90AA1, Hsp90AB1, TRAP1, HspA5, HspB1, HspE1, HspD1, HspA1B, HspA8, HspA9, and HspA4, were significantly upregulated in breast cancer tissue." (PMID 31921692, 2019). "Heat shock proteins showed the most significant change of all the upregulated domains, with Hsp90AA1, Hsp90AB1, TRAP1, HspA5, HspB1, HspE1, HspD1, HspA1B, HspA8, HspA9, and HspA4 identified in breast cancer tissue." (PMID 31921692, 2019). "The co-expression network revealed that ELAVL2, VIM, MRPS12, HSPE1, EZH2, HIST1H4B, and MRPL13 played a vital role in the progression of breast cancer, and we further selected important modules of target genes through MCODE." (PMID 30881302, 2019). "Coming back to HSPE1, in a previous proteomic analysis this protein appeared with altered expression in MDA-MB-231 breast cancer cells (triple negative highly aggressive cells) and both HSPD1/HSPE1 have also been found upregulated in other cancer types associated with tumour cell transformation." (PMID 29954368, 2018).
ovarian carcinoma (4 papers, 2015 to 2025). A malignant neoplasm originating from the surface ovarian epithelium. "The Kaplan‒Meier plotter database results showed that high expression of TFAM, HSPE1, and CYC1 was associated with an overall poor prognosis in ovarian cancer." (PMID 39927160, 2025). "In humans, extracellular HSPE1 has been reported to act as a suppressor of antitumor immunity in ovarian cancer." (PMID 30112103, 2018). "The protein levels of TFAM, HSPE1, and CYC1 were significantly increased in ovarian cancer tissues compared with normal tissues." (PMID 39927160, 2025). "Furthermore, the protein levels of TFAM, HSPE1, and CYC1 varied according to clinical stages of ovarian cancer." (PMID 39927160, 2025). "Although the TFAM and HSPE1 total protein expression levels of ovarian cancer tissues of each clinical stage were higher than those of normal tissues, the difference was only significant between normal and stage 3 tissues." (PMID 39927160, 2025). "The results from the TCGA database showed that HSPE1 and CYC1 were significantly upregulated in ovarian cancer tissues, but TFAM was not statistically significant." (PMID 39927160, 2025).
bladder cancer (3 papers, 2018 to 2025). "HSPE1 modulates ferroptosis by regulating GPX4/lipid peroxidation in bladder cancer and promotes LUAD malignancy via aerobic glycolysis." (PMID 41375045, 2025). "ANXA3 (annexin A3) and HSPE1 (heat shock protein family E member 1), which showed the highest detection frequency in bladder cancer samples, were selected for further validation." (PMID 30112103, 2018). "According to the result of ELISA assay (n = 126 for bladder cancer), HSPE1 was detectable in 97 bladder cancer urine specimens." (PMID 30112103, 2018). "And HSPE1 was up-expressed (cut-off value = 0.07414 ng/ml) in 95 out of 126 (75.4%) bladder cancer urine samples." (PMID 30112103, 2018). "HSPE1 is a member of the heat shock protein family (Hsp10) E, which usually acts as a chaperone to assist protein folding in the mitochondria, which is highly expressed in various cancers, such as lung cancer, pancreatic cancer and bladder cancer." (PMID 30881302, 2019). "To further confirm the utility of HSPE1 as a non-invasive biomarker for BC diagnosis, we measured the concentration of HSPE1 in a large number of urine specimens from 142 hernia, 126 bladder cancer, 67 hematuria, and 59 urinary tract infection patients by sandwich ELISA." (PMID 30112103, 2018). "Western blotting showed that urinary ANXA3 and HSPE1 protein levels were higher in bladder cancer samples than in hernia samples, and enzyme-linked immunosorbent assays confirmed a higher urinary concentration of HSPE1 in bladder cancer than in hernia, hematuria and urinary tract infection." (PMID 30112103, 2018). "Additionally, correlation analyses between urinary HSPE1 expression and clinicopathological characteristics of urine specimens from bladder cancer patients were assessed using a Chi-squared test." (PMID 30112103, 2018). "Immunohistochemical analyses showed significantly elevated levels of HSPE1 in tumor cells compared with non-cancerous bladder epithelial cells, suggesting that HSPE1 could be a useful tumor tissue marker for the specific detection of bladder cancer." (PMID 30112103, 2018).
Obesity (3 papers, 2020 to 2025). Accumulation of substantial excess body fat. "HSPE1 was associated with obesity, inflammation and NETs release." (PMID 38919521, 2024).
Parkinson disease (3 papers, 2021 to 2026). A progressive degenerative disorder of the central nervous system characterized by loss of dopamine producing neurons in the substantia nigra and the presence of Lewy bodies in the substantia nigra and locus coeruleus. "Indeed, it has been shown that Hsp10 expression is reduced in the putamen of Parkinson’s disease (PD) patients, and a missense mutation in HSPE1 is associated with a neurodegenerative disease, highlighting the potential protective role of Hsp10 for neuronal health." (PMID 33946318, 2021).
Sepsis (3 papers, 2017 to 2024). Sepsis is defined as life-threatening organ dysfunction caused by a dysregulated host response to infection. "Our PPI network analysis further unveils several key regulators like TOP2A, PAICS, HSPE1, HSP90AA1 and ACACA in the central hubs of dysregulated gene network in sepsis-induced ARDS." (PMID 33904373, 2021).
developmental delay (2 papers, 2016 to 2021). "Exome sequencing of the patient with infantile spasms and developmental delay described here detected heterozygosity for a de novo mutation in the HSPE1 gene and chromosomal microarray analysis detected a de novo deletion affecting the TANC2 gene." (PMID 27774450, 2016). "In a similar way, a heterozygous mutation in the HSPE1 gene ( coding for the protein HSP10) (p.L73F) was found in a patient with neurological and developmental disorder including spasms, hypotonia, developmental delay, and macrocephaly." (PMID 34356047, 2021).
endometrial cancer (2 papers, 2016 to 2024). Primary or metastatic malignant neoplasm involving the endometrium (mucous membrane that lines the endometrial cavity). "HSPE1, SERPINA1 and PKM2 constitute the panel of proteins that satisfactorily differentiate endometrial cancer and normal endometrium." (PMID 39194522, 2024).
glaucoma (2 papers, 2019 to 2024). Increased pressure in the eyeball due to obstruction of the outflow of aqueous humor. "On the contrary, the proteins HSP90AA1, HSPE1 and ERP29 are mainly functional as molecular chaperone complexes essential for the maintenance of the protein folding and protein trafficking, during cellular stress responses and are a hallmark for various neurodegenerative diseases, including glaucoma." (PMID 31443184, 2019).
glial tumors (2 papers, 2022 to 2025). "Specifically, we provided functional evidence that HSPE1 played an essential role in glioma progression." (PMID 41035644, 2025). "Crucially, HSPE1 knockdown significantly suppressed the proliferation and invasion of glioma cell lines." (PMID 41035644, 2025). "In U87 and U251 glioma cell models, we successfully knocked down HSPE1 expression, as verified by qPCR and Western blot analysis." (PMID 41035644, 2025). "Experimental validation of HSPE1 revealed its crucial role in glioma progression, supporting its potential as a therapeutic target." (PMID 41035644, 2025). "Critically, functional validation confirmed HSPE1 as a pro-oncogenic driver, where its silencing suppressed glioma cell proliferation and invasion in vitro." (PMID 41035644, 2025). "Our findings established that HSPE1 was a key player in glioma progression, and its upregulation contributed to tumor growth and invasiveness." (PMID 41035644, 2025). "This experimental validation strengthened the translational potential of our findings and provided a direct link between computational predictions and experimental biology, highlighting HSPE1 as a promising therapeutic target for glioma treatment." (PMID 41035644, 2025). "Given that HSPE1, a core LRGs gene, demonstrated the highest hazard ratio in multivariate Cox analysis, exhibited high expression abundance in malignant cells, and has an undefined functional role in gliomagenesis, we selected HSPE1 for further investigation into its ability to affect glioma cells." (PMID 41035644, 2025). "Furthermore, we demonstrated that HSPE1 knockdown significantly inhibited the proliferation and invasion of glioma cells." (PMID 41035644, 2025). "However, the functional role of HSPE1 in glioma has remained unclear until now." (PMID 41035644, 2025). "Furthermore, we identified HSPE1 as a critical driver of glioma progression." (PMID 41035644, 2025). "This analysis confirmed significantly upregulation of LRGs score and its core genes (KIF2C, CALD1, HSPE1, and IFI16) in glioma versus normal tissues." (PMID 41035644, 2025). "In vitro validation of the oncogenicity of HSPE1 was conducted using the CCK-8, colony formation, transwell, and apoptosis assays in U87 and U251 glioma cells." (PMID 41035644, 2025).
serous ovarian cancer (2 papers, 2017 to 2025). "First, analysis of EOC RNA-seq data (GSE209964) from the GEO database showed that the mitochondrial genes TFAM, HSPE1, and CYC1 were significantly upregulated in high-grade serous ovarian cancer." (PMID 39927160, 2025).
bipolar disorder (1 paper, 2024). A disorder of the brain that causes unusual shifts in mood, energy, activity levels and the ability to carry out day-to-day tasks. "Genes that were associated with brain volumes, depression, and schizophrenia or bipolar disorder includedAC011997.1,AKT3,BANK1,BOLL,DCC,HSPD1,HSPE1,HSPE1-MOB4,MOB4,PLCL1,RFTN2,SF3B1, andTRPS1." (PMID 40800518, 2024).
bladder tumor (1 paper, 2018). "IHC scoring results indicate that HSPE1 expression levels in bladder tumor tissues were ~2.9-fold higher than those in normal tissues (P < 0.0001)." (PMID 30112103, 2018).
cataract (1 paper, 2023). Partial or complete opacity of the crystalline lens of one or both eyes that decreases visual acuity and eventually results in blindness. "Lastly, although functional models are needed to prove the pathogenicity of the variants, the important role played by the HSPE1 and ODF1 genes in the lens and the de novo presence of the variants in the proband led us to propose both genes as causal for pediatric cataracts." (PMID 37511188, 2023).
COVID-19 (1 paper, 2024). A disease caused by infection with severe acute respiratory syndrome coronavirus 2. "Indeed, it was reported that the HSPD1-derived altered peptide ligand reduced the pro-inflammatory cytokines in rheumatoid arthritis disease and also in COVID-19 patients; in addition, HSPE1 inhibited lipopolysaccharide-induced inflammation by interacting with HSPD1." (PMID 38200905, 2024).
cryptorchidism (1 paper, 2018). The failure of one or both testes of a male fetus to descend from the abdomen into the scrotum during the late part of pregnancy. "Hspe1 showed > 3.0 fold up-regulation in heat stressed round spermatids and its companion protein Hspd1 was up-regulated (3.2 fold) after 120 h of cryptorchidism." (PMID 29859541, 2018).
depression (1 paper, 2024). "Ten genes were associated with depression, ICV, and the volume of the hippocampus, among them Heat Shock Protein Family E (Hsp10) Member 1 (HSPE1), MOB Family Member 4, Phocein (MOB4), and Coenzyme Q10B (COQ10B)." (PMID 40800518, 2024).
diabetes (1 paper, 2024). "However, HSPD1 was also found to be upregulated and to act as an initiator of oxidative stress and neuroinflammation in diabetes, and HSPE1 stimulated mitochondrial stress and damaged the mitochondrial structure of chondrocytes." (PMID 38200905, 2024).
Hematuria (1 paper, 2018). The presence of blood in the urine. "Additionally, the concentration of HSPE1 in urine from BC patients was 3.49- and 3.86-fold higher than that in urine from hematuria and UTI patients, respectively." (PMID 30112103, 2018). "Notably, our ELISA result revealed that the level of HSPE1 in BC urine specimens was higher than hernia, hematuria and UTI, which may be able to overcome the interferences of hematuria." (PMID 30112103, 2018).
Hernia (1 paper, 2018). "The concentration of HSPE1 in urine from BC patients was 2.5-fold higher than that in urine from hernia patients (P < 0.01, total n = 268)." (PMID 30112103, 2018). "The urinary concentration of HSPE1 in early-stage and low-grade BC were both significantly higher (at least 2.46-fold) than that in hernia." (PMID 30112103, 2018). "Western blotting indicated that the urinary concentration of HSPE1 was significantly higher (~4.7-fold) in individual BC patients than in hernia patients (P < 0.05, n = 16)." (PMID 30112103, 2018). "Here, we found that urinary expression of HSPE1, which can also be measured in human blood, was greater in BC patients than in other non-cancer control conditions, including hernia, hematuria, and UTI." (PMID 30112103, 2018).
urinary tract infection (1 paper, 2018). "We further evaluated the effect of blood contamination and urinary tract infection in urinary HSPE1 concentration of BC patients." (PMID 30112103, 2018).
urothelial carcinoma (1 paper, 2018). A malignant neoplasm derived from the transitional epithelium of the urinary tract (urinary bladder, ureter, urethra, or renal pelvis). "Because ANXA3 has been reported to be a biomarker for other urothelial carcinomas, we focused on HSPE1 expression in clinical samples, validating its concentration level in individual urine samples." (PMID 30112103, 2018).